IL6R (interleukin 6 receptor)
Description:
Part of the receptor for interleukin 6. Binds to IL6 with low affinity, but does not transduce a signal. Signal activation necessitate an association with IL6ST. Activation leads to the regulation of the immune response, acute-phase reactions and hematopoiesis. The interaction with membrane-bound IL6R and IL6ST stimulates 'classic signaling', the restricted expression of the IL6R limits classic IL6 signaling to only a few tissues such as the liver and some cells of the immune system. Whereas the binding of IL6 and soluble IL6R to IL6ST stimulates 'trans-signaling'. Alternatively, 'cluster signaling' occurs when membrane-bound IL6:IL6R complexes on transmitter cells activate IL6ST receptors on neighboring receiver cells (Probable). [Isoform 1]: Signaling via the membrane-bound IL6R is mostly regenerative and anti-inflammatory (Probable). Drives naive CD4(+) T cells to the Th17 lineage, through 'cluster signaling' by dendritic cells (By similarity). [Isoform 2]: Soluble form of IL6 receptor (sIL6R) that acts as an agonist of IL6 activity. The IL6:sIL6R complex (hyper-IL6) binds to IL6ST/gp130 on cell surfaces and induces signaling also on cells that do not express membrane-bound IL6R in a process called IL6 'trans-signaling'. sIL6R is causative for the pro-inflammatory properties of IL6 and an important player in the development of chronic inflammatory diseases. In complex with IL6, is required for induction of VEGF production. Plays a protective role during liver injury, being required for maintenance of tissue regeneration (By similarity). 'Trans-signaling' in central nervous system regulates energy and glucose homeostasis (By similarity). [Soluble interleukin-6 receptor subunit alpha]: Soluble form of IL6 receptor (sIL6R) that acts as an agonist of IL6 activity. The IL6:sIL6R complex (hyper-IL6) binds to IL6ST/gp130 on cell surfaces and induces signaling also on cells that do not express membrane-bound IL6R in a process called IL6 'trans-signaling'. sIL6R is causative for the pro-inflammatory properties of IL6 and an important player in the development of chronic inflammatory diseases. In complex with IL6, is required for induction of VEGF production. Plays a protective role during liver injury, being required for maintenance of tissue regeneration (By similarity). 'Trans-signaling' in central nervous system regulates energy and glucose homeostasis (By similarity).
Synonyms: IL-6RA; gp80; CD126; IL-6R; IL-1Ra; IL6RA; HIES5; IL-6R-1; IL6Q; IL6QTL; IL6RQ
Tractability: Small molecule: a structure with a bound ligand is known. Antibody: an approved drug acts on it; UniProt places it where antibodies can reach, with high confidence; its Gene Ontology location is reachable by antibodies, with high confidence; UniProt predicts a signal peptide or a membrane-spanning region.
Target class: Secreted protein
Gene: Protein-coding gene on chromosome 1 (154,405,193 to 154,469,450, forward strand). Ensembl gene ENSG00000160712.
Subcellular location: Cell membrane (Isoform 1); Secreted (Isoform 2); Secreted (Soluble interleukin-6 receptor subunit alpha)
Pathways (Reactome):
Immune System: Interleukin-4 and Interleukin-13 signaling; Interleukin-6 signaling
Signal Transduction: MAPK1 (ERK2) activation; MAPK3 (ERK1) activation
Cell-Cell communication: Activation of STAT3 by cadherin engagement
Developmental Biology: Transcriptional regulation of granulopoiesis
Disease: Potential therapeutics for SARS
Gene Ontology:
Molecular function: ciliary neurotrophic factor binding; ciliary neurotrophic factor receptor activity; enzyme binding; interleukin-6 binding; interleukin-6 receptor activity; interleukin-6 receptor binding; protein binding; protein homodimerization activity; interleukin-11 binding; interleukin-11 receptor activity; cytokine receptor activity
Biological process: cell surface receptor signaling pathway via STAT; ciliary neurotrophic factor-mediated signaling pathway; cytokine-mediated signaling pathway; endocrine pancreas development; interleukin-6-mediated signaling pathway; positive regulation of cell population proliferation; positive regulation of chemokine production; positive regulation of glomerular mesangial cell proliferation; positive regulation of interleukin-6 production; positive regulation of smooth muscle cell proliferation; response to cytokine; vascular endothelial growth factor production; acute-phase response; defense response to Gram-negative bacterium; extrinsic apoptotic signaling pathway; hepatic immune response; monocyte chemotaxis; positive regulation of leukocyte chemotaxis; positive regulation of osteoblast differentiation; developmental process; interleukin-11-mediated signaling pathway
Cellular component: apical plasma membrane; ciliary neurotrophic factor receptor complex; extracellular region; interleukin-6 receptor complex; external side of plasma membrane; plasma membrane; receptor complex; membrane
Genetic constraint (gnomAD): Loss-of-function variants: 30 observed, 42.17 expected, observed/expected ratio (o/e) 0.71, 90% interval 0.53 to 0.96. The upper end of that interval is the gene's LOEUF score, 0.96, which puts it in group 4 of 6, group 1 being the genes least tolerant of losing a copy. Missense variants: 480 observed, 568.6 expected, observed/expected ratio (o/e) 0.84, 90% interval 0.78 to 0.91. Synonymous variants: 252 observed, 243.01 expected, observed/expected ratio (o/e) 1.04, 90% interval 0.94 to 1.15.
Gene-disease validity (ClinGen):
ClinGen rates the evidence that IL6R causes each of these diseases.
hyper-IgE recurrent infection syndrome 5, autosomal recessive (autosomal recessive): Limited.
Homologues: Orthologues: macaque IL6R (93% identical), chimpanzee IL6R (91% identical), pig IL6R (75% identical), dog IL6R (75% identical), guinea pig IL6R (66% identical), rabbit IL6R (63% identical), mouse Il6ra (54% identical), rat Il6r (47% identical), tropical clawed frog il6r (26% identical), zebrafish lifra (12% identical), zebrafish lifrb (11% identical), zebrafish il11ra (9% identical), and 3 more. Paralogues in human: CNTFR (17% identical), IL12RB2 (17% identical), CSF3R (16% identical), IL11RA (16% identical), IL2RG (15% identical), LIFR (15% identical), IL6ST (13% identical), OSMR (12% identical), IL31RA (12% identical), CRLF1 (11% identical), IL27RA (11% identical), PRLR (11% identical), and 11 more.
Diseases named in the same sentence as IL6R in open-access papers:
IL6R is named in the same sentence as 484 diseases in open-access papers, as found by Europe PMC text mining. Sharing a sentence is not in itself a finding about the gene and the disease. The quoted sentences say what the papers report.
COVID-19 (260 papers, 2020 to 2026). A disease caused by infection with severe acute respiratory syndrome coronavirus 2. "The SR was associated with previous mild acute COVID-19 and with an SNP (rs2228145) in IL6R related to low gene expression." (PMID 39201427, 2024). "Thereby, we aimed to investigate the association of IL-1β (rs16944 and rs1143634) and IL-6R (rs12083537) SNPs with COVID-19 severity among the Egyptian population." (PMID 39452786, 2024). "We aimed to investigate the association of IL-6R rs12083537, IL-1β rs16944, and IL-1β rs1143634 SNPs with the severity of COVID-19." (PMID 39452786, 2024). "Another study on an Amazonian population pointed to the presence of a consistent link between the polymorphisms of IL-6 and its receptor (IL-6R) with COVID-19 severity." (PMID 39452786, 2024). "The IL-1β (rs16944) CC genotype and IL-6R (rs12083537) GG genotype were substantially related to COVID-19 severity, which was also associated with comorbidities and some laboratory parameters (p < 0.001)." (PMID 39452786, 2024). "The IL-1β rs1143634 SNP T allele was protective against severe COVID-19, while the IL-6R rs12083537 G allele and the IL-1β rs16944 C allele were markedly related to COVID-19 severity among Egyptians." (PMID 39452786, 2024). "Genetic variations in the IL6R target associated with inhibitors were linked to a reduced risk of rheumatoid arthritis and COVID-19." (PMID 39229261, 2024). "The COVID-19 cases were significantly associated with IL-6R rs12083537AG, GG genotypes, and the G allele." (PMID 39452786, 2024). "Thereby, the main perspective of our work was to study the association of three substantial gene polymorphisms (IL-6R rs12083537, IL-1β rs16944, and IL-1β rs1143634) with COVID-19 severity among Egyptian patients." (PMID 39452786, 2024). "Nine patients (3.1%) received tocilizumab, a monoclonal antibody targeting the interleukin-6 receptor, which has shown efficacy in managing cytokine release syndrome associated with severe COVID-19." (PMID 38186472, 2023). "Findings showed that IL-6 receptor (IL-6R) variants mimicking therapeutic inhibition of IL-6R are associated with lower risk of being hospitalized for COVID-19, a phenotype that correlates with disease severity." (PMID 37278822, 2023). "Carriers of certain single nucleotide polymorphisms (SNPs) around and in the IL6R gene (the target for IL6RAs) that phenocopy IL6RA function have a reduced risk of becoming critically ill with COVID-19." (PMID 36716318, 2023). "Genetic variants in IL6R known to down-regulate IL-6 signalling are associated with improved Coronavirus Disease 2019 (COVID-19) outcomes, a finding later confirmed in randomised trials of IL-6 receptor antagonists (IL6RAs)." (PMID 36716318, 2023). "In line with this, tocilizumab, an IL-6R inhibitor, has been associated with improved outcomes in critically ill COVID-19 patients." (PMID 35806986, 2022). "Nonetheless, a recent study evaluating the anti-IL6R antibodies tocilizumab and sarilumab demonstrated some improvement in survival when treating critically ill COVID-19 patients, even more so when these drugs were associated with dexamethasone." (PMID 34293006, 2021). "Due to their widespread use, in this paper we will be focusing specifically on the anti-IL-6/IL-6R mAbs and their use in the treatment of the COVID-19-associated cytokine storm." (PMID 34073559, 2021). "The IL-6 binding to the IL-6R sub-unit has been implicated in cytokine storm occurrence in the COVID-19 pathology." (PMID 34683938, 2021). "Genetically predicted soluble IL-6R was only associated with higher risk of hospitalised COVID-19 compared to population-based controls (cis-MR OR [95% CI] per SD genetically predicted IL-6R: 0.94 [0.91, 0.97], p=8 × 10–4)." (PMID 34402426, 2021).
COVID-19 (continued). "Although the PP.H4 of IL-6R was very weak (0.4), it had a positive (H4/H3 = 3.6), indicating a common signal of the IL-6R protein with the COVID-19 outcome is a more likely scenario than the association driven by two independent signals." (PMID 34402426, 2021). "In COVID-19 cases, colonic perforation caused by interleukin-6 receptor antagonist therapy was also reported." (PMID 34347185, 2021). "Ingenuity Pathway Analysis (IPA) showed that IL6 and IL6R appeared to be implicated in several pathogenetic mechanisms associated with COVID-19 severity and mortality as well as with neurodegenerative diseases mediated by neuroinflammation." (PMID 33339153, 2020). "Levels of serum IL-6 and IL-6 receptors (IL-6R) were significantly elevated in patients with COVID-19, and were closely associated with respiratory failure, acute respiratory distress syndrome, secondary infections, and death." (PMID 33384605, 2020). "Insights into the link between the Interleukin-6 receptor (IL-6R) and Interleukin-1 beta (IL-1β) genetic variation and severe coronavirus disease 2019 (COVID-19) are crucial for developing new predictors and therapeutic targets." (PMID 39452786, 2024). "Intriguingly, the number of known pre-existing conditions was also highly correlated with IL-6 (r=0.25, p<0.01), sIL-6R (r=0.21, p<0.05) and sgp130 (r=0.29, p<0.01) serum levels, underlining that pre-existing diseases are an important predictor of COVID-19 disease course." (PMID 39835136, 2024). "Furthermore, this beneficial effect of IL6R blockade in COVID-19 was anticipated in a causal framework analysis using genetic data." (PMID 36716318, 2023). "We performed a Mendelian randomisation (MR) analysis using single nucleotide polymorphisms (SNPs) in and near IL6R to evaluate the likely causal effects of IL6R blockade on sepsis (primary outcome), sepsis severity, other infections, and COVID-19 (secondary outcomes)." (PMID 36716318, 2023). "We believe risk stratification to be of paramount importance for COVID-19 patients, as patients with the highest values may benefit most from anti-viral or anti-inflammatory therapies such as steroids, interleukin-6 receptor antagonists, or anti-JAK molecules." (PMID 36139946, 2022). "While these loci may hold biological plausibility (especially IL6R, given the use of IL-6 receptor inhibitors in the treatment of COVID-19), these associations were driven by two smaller cohorts (Genentech and Vanda)." (PMID 36327219, 2022). "IL6R expression was increased in the pathogenic process of COVID-19." (PMID 35541915, 2022). "A large proportion of our patients (85.5%) received tocilizumab (anti-interleukin-6 receptor) according to our hospital protocol treatment for COVID-19 patients (pneumonia with bilateral involvement associated with elevated interleukin-6 and C-reactive protein, requiring oxygen therapy)." (PMID 34068847, 2021). "IL-6, in particular, has been highly implicated in CRS and COVID-19 severity, and inhibition of IL-6/IL-6R activity may lead to improved patient outcome, increasing its desirability as a target." (PMID 33733182, 2020). "Our results showed that a blockade of IL-6 signaling by anti-IL-6/IL-6R/JAK antibodies plus SOC significantly reduced the mortality rate but did not increase the risk of secondary infections compared to SOC alone in patients with COVID-19." (PMID 33384605, 2020). "The association of IL6R gene polymorphisms with the effectiveness of tocilizumab was found in rheumatoid arthritis and was recently investigated in patients affected with COVID-19." (PMID 32917282, 2020). "Additionally, a small group of patients received tocilizumab, an interleukin-6 receptor antagonist, which has been considered in COVID-19 patients in an effort to reduce the inflammation associated with CRS." (PMID 32835113, 2020).
COVID-19 (continued). "A recent study found that patients with acute COVID-19 who later developed Long COVID had higher IL-6 levels during the acute phase indicating than those who fully recovered, demonstrating that carrying the IL-6R AA genotype had a higher risk of developing Long COVID." (PMID 40087795, 2025). "However, the role of IL-6R in the CRS associated with COVID-19 and as a treatment target remains unclear." (PMID 38165854, 2024). "Hence, some studies claim that the blockade of IL-6R could be beneficial in COVID-19 therapy protocols and even consider the influence of IL6R polymorphism in these protocols." (PMID 37243282, 2023). "Genetically mimicking IL6R blockade using genetic instruments from the IL6R gene strongly associated with c-reactive protein was associated with lower risk of hospitalized COVID-19, but whether these associations are due to IL-6, IL-6R, or pleiotropic effects via other mechanisms is unclear." (PMID 34163532, 2021). "In the present study, we investigated the distribution of copy number variations (CNVs) and genetic variants located within the coding sequences of IL6 and IL6R genes, which may be employed as prognostic and drug response (pharmacogenetic) biomarkers for COVID-19 and neuroinflammatory diseases." (PMID 33339153, 2020). "Contrary to our findings, a reduced expression of miR-451a has been previously found in COVID-19 patients, where miR451a was described as a down-regulator of the interleukin 6 receptor (IL6R), contributing to the cytokine storm characteristic of this disease." (PMID 39943201, 2025). "Tocilizumab, an IL-6R inhibitor, only partially reverses the metabolic consequences of severe COVID-19." (PMID 41002992, 2025). "IL-6 is an effective therapeutic target in inflammatory diseases and tocilizumab, a monoclonal antibody that blocks signaling via the IL-6 receptor (IL-6R), is used to treat patients with severe COVID-19." (PMID 39835136, 2024). "The principal finding in our study was an increased frequency of IL-6R rs12083537 GG genotypes among COVID-19 patients with a significant relationship to disease severity." (PMID 39452786, 2024). "Sarilumab (monoclonal antibody blocking IL-6R) efficacy was previously assessed in patients with coronavirus disease 2019 (COVID-19) (NCT04315298)." (PMID 38795859, 2024). "Remdesivir is also recommended in combination with other adjuncts such as interleukin 6 receptor or Janus kinase inhibitors (eg, baricitinib) in patients with rapidly progressing COVID-19, even if they were started on mechanical ventilation." (PMID 39405443, 2024). "This study identified 30 nodes associated with cytokine storm, ARDS, and inflammatory process of COVID-19, namely, IL-6, IL-6R, NF-κB, IL-2, IL-2RA, IFNA2, IFNAR1, COX5A, and COX411." (PMID 39640429, 2024). "In this Swedish nationwide study including IRD patients three and four COVID-19 vaccine doses were immunogenic in patients treated with IL6r inhibitors, TNF-inhibitors, JAK-inhibitors, and IL12/23/17-inhibitors but not in rituximab." (PMID 38441463, 2024). "AGE and SFN treatment had the same effect as an antagonist of IL-6R, the neutralizing antibody suggested for treating advanced COVID-19." (PMID 38807598, 2024). "For example, miR-451a is an IL-6R translational repressor that exacerbates the IL-6-induced cytokine storm and one of the top five downregulated microRNA genes in COVID-19 patients." (PMID 38932387, 2024). "The overproduction of IL-6 inhibits NK cell cytotoxicity, as confirmed by the in vivo treatment with therapeutic anti-IL-6R mAb, which increases NK cell function in COVID-19 patients." (PMID 38881905, 2024). "The CSF2, IFNG, and IL1B expression levels were considerably lower in the COVID-19 than in the Healthy group, while those of IL6R, TLR2, TLR4, and TNF were higher." (PMID 38165854, 2024). "The remaining IL6R, IFNG, TLR4, and TLR2 genes (feature gene) were the most likely COVID-19 pathogenic genes that progressed into CRS." (PMID 38165854, 2024).